APOE (apolipoprotein E)
Diseases named in the same sentence as APOE in open-access papers (continued):
Sharing a sentence is not in itself a finding about the gene and the disease.
Alzheimer disease (continued). "Moreover, rs429358 and rs481778 located in APOE and PLEKHA4 genes on chromosome 19 are related to Alzheimer disease." (PMID 36859360, 2023). "Age, Mini-Mental State Examination (MMSE), cognitive subscale of the Alzheimer’s Disease Assessment Scale (ADAS-cog), apolipoprotein E (APOE), standardized uptake value ratio (SUVR), AV45_BASS, MR_BAI, and shape feature were significantly different between converters and non-converters." (PMID 37958271, 2023). "The independent and interactive effect of APOE genotype and HRT use on select cognitive function tests and medial temporal lobe–related MRI brain volumes was tested cross-sectionally in the European Prevention of Alzheimer’s Dementia (EPAD) cohort." (PMID 36624497, 2023). "There are three isoforms of APOE that differ in amino acids 112 and 158, with APOE3 (Cys112, Arg158) being the basic one, while APOE4 (Arg112, Arg158) is known to increase the incidence of Alzheimer’s disease." (PMID 38201273, 2023). "Alzheimer disease PRS with (P = 2.6 × 10–85) and without (P = 1.4 × 10–19) APOE showed a strong association with amyloid imaging." (PMID 37101235, 2023). "APOE and GSAD were each associated with all-cause (p < 0.0001) and Alzheimer’s dementia (p < 0.0001) but did not modify the associations between MIND/AHEI and dementia (p > 0.05 for interaction)." (PMID 36615690, 2022). "Considering the best biometrical model, directly measured APOE ɛ4 explained 9.3% and PRS.no.APOE an additional 2.1% of Alzheimer’s disease risk, leaving much of the genetic risk uncaptured (i.e. 71.1% total minus 11.4% measured)." (PMID 35169705, 2022). "When APOE ɛ4 alleles were added to the model with the PRS.no.APOE, the total contribution was 11.4% to Alzheimer’s disease risk, where APOE ɛ4 explained 9.3% and PRS.no.APOE dropped from 2.4 to 2.1%." (PMID 35169705, 2022). "APOE*4 is now a confirmed risk factor for DLB, independent of any co-morbid Alzheimer’s disease pathology." (PMID 35052839, 2022). "The APOE ɛ4 allele and minor alleles of rs2075650 TOMM40 and rs12721046 APOC1 variants confer a higher risk of Alzheimer's disease compared with the ɛ4 allele and no minor alleles of these two polymorphisms." (PMID 36330582, 2022). "A previous study revealed differences in myo-inositol levels between APOE ε4 carriers and non-carriers already in preclinical Alzheimer’s disease participants." (PMID 35702728, 2022). "Moreover, the association of high amyloid burden and loneliness has been shown to be stronger in APOE ε4 carriers than in noncarriers, indicating that individuals with genetic risk for Alzheimer’s disease may be at greater risk of loneliness and social isolation." (PMID 34299756, 2021). "In addition, inhibition of miR-33-5p lowered the endogenous cortical level of amyloid-β in a mouse model of Alzheimer’s disease (AD) via increased ABCA1 expression and APOE lipidation, suggesting a potential therapeutic strategy for AD32." (PMID 34131232, 2021). "For Alzheimer’s disease, allelic heterogeneity was observed in the genomic locus containing NECTIN2, TOMM40, APOE and APOC1, which has been reported before and reflects the fact that different APOE haplotypes ε2, ε3 or ε4 can be risk factors or protective factors for Alzheimer’s disease." (PMID 34326310, 2021). "Except for IL-6 and IL-13, brain cytokine level was not related to possession of APOE ε4 in either controls or Alzheimer’s disease brains (Supplementary)." (PMID 33723589, 2021). "One way APOE genotype could impact neuronal function is through neurovascular disruption, which is found with APOE4 during aging, in Alzheimer’s disease and in respective mouse models." (PMID 34178992, 2021). "A meta-analysis showed APOE e4 genotype prevalence varies among the population diagnosed with Alzheimer’s disease (AD) by geographic region, with the highest estimates in Northern Europe and the lowest estimates in Asia and Southern Europe." (PMID 34970595, 2021).
Alzheimer disease (continued). "Specific for APOE, in the Alzheimer’s Disease Cooperative Study (ADCS), DHA failed to impact learning and memory in all patients; however, there was an indication of a beneficial effect in APOE4 non-carriers." (PMID 34276296, 2021). "Finally, we investigated if the APOE genotype and DHA interact to predict volumes of other Alzheimer’s disease vulnerable brain regions in the human spatial navigation network, namely the precuneus and posterior cingulate cortex." (PMID 34007965, 2021). "Prior evidence suggested Apolipoprotein E (APOE), lipids, and glucose metabolism may act through the same pathways on the pathogenesis of Alzheimer’s disease (AD)." (PMID 34483892, 2021). "Non-Mendelian Alzheimer’s disease (AD) has become the paradigm of a complex disease for which a major genetic determinant is known, the APOE locus." (PMID 33846280, 2021). "Thirty-five subjects with a family history of Alzheimer disease (AD) (FH+) and ApoE ɛ4 carriers and 29 age-matched control subjects without a family history of AD (FH−) and ApoE ɛ4 non-carriers were included." (PMID 32503282, 2020). "Our results most closely match those from the Alzheimer’s Disease Neuroimaging Initiative, Australian Imaging, Biomarker and Lifestyle Study, and Harvard Aging Brain Study, which showed that APOE ε4 itself is not a major factor in clinical progression." (PMID 32885039, 2020). "The IMI ADAPTED (The Alzheimer’s Disease Apolipoprotein Pathology for Treatment Elucidation and Development) is an Innovative Medicine Initiative (IMI) that aims to improve the understanding about the role of APOE gene in AD." (PMID 32427856, 2020). "Notably, the apolipoprotein E (APOE) ε4 carrying status and Mini-Mental State Examination (MMSE) and Alzheimer's Disease Assessment Scale-Cognitive Subscale (ADAS-Cog) scores were significantly different." (PMID 32726298, 2020). "In the models using an Alzheimer’s disease PGS with the APOE region included, having one copy of APOE-ε4 increased the odds of dementia relative to normal cognition by roughly twofold, while two copies of APOE-ε4 increased the odds of dementia by over fourfold, holding all other variables constant." (PMID 33143703, 2020). "Demographic and clinical data of patients with Alzheimer’s disease grouped based on APOE-ε4 carriers versus non-carriers or FGF1-rs34011-GG (GG-carriers) versus FGF1-rs34011-A-allele carriers (A-allele-carriers)." (PMID 31164996, 2019). "To achieve this, we isolated synaptoneurosomes from post-mortem tissue of Alzheimer's disease and non-demented control individuals of known APOE genotypes which were then probed for clusterin levels." (PMID 31853523, 2019). "The relation of PBV and APOE to the diagnosis of Alzheimer’s disease (AD) and mild cognitive impairment (MCI) versus no cognitive impairment (NCI) was examined using an ordered logistic regression model." (PMID 31022959, 2019). "Rs1990622 also has been associated with cognitive impairment in amyotrophic lateral sclerosis (ALS), hippocampal sclerosis in normal aging, and incidence of Alzheimer’s disease (AD) in APOE ε4 negative individuals." (PMID 30390709, 2018). "The precise biological mechanism linking APOE genotype and Alzheimer’s disease, however, is not well-understood." (PMID 30339707, 2018). "By contrast, we find APOE in Alzheimer’s disease and tauopathies in the connected subgraph and not TOMM40, which indicates a greater mechanistic relevance of APOE for the disease than TOMM40." (PMID 27748412, 2016). "Comment: This patient presented with typical type 3 Alzheimer's disease, with the single exception that his ApoE genotype was not ε4-negative." (PMID 26870879, 2016). ", showing that the differences in APOE methylation between individuals with and without Alzheimer's disease increases with age." (PMID 25476875, 2015).
Alzheimer disease (continued). "Finally, apolipoprotein E (APOE) has been proposed to alter the risk of Parkinson’s disease dementia as well as being a risk factor for Alzheimer’s disease, even if it does not significantly alter the risk of developing Parkinson’s disease without Parkinson’s disease dementia." (PMID 25080285, 2014). "There was also a statistically significant main effect of amyloid status (P<0.001), but no significant main effect of APOE ε4 genotype (P = 0.33), on Alzheimer's Disease Assessment Scale-Cognitive Subscale." (PMID 24736891, 2014). "GWAS of late-onset Alzheimer’s disease (LOAD), a genetically complex disease with an estimated 60-80% heritability, have identified common SNPs which reach genome-wide significance at the well-known APOE locus and at nineteen additional loci." (PMID 24607147, 2014). "APOE genotype, a family history of Alzheimer's disease, and age did not influence cortical thickness." (PMID 24228185, 2013). "APOE genotype, a first-degree family history of Alzheimer's disease, and age did not influence regional medial temporal lobe cortical thickness in our sample." (PMID 24228185, 2013). "ApoE, ApoE receptors and APP cooperate in the pathogenesis of Alzheimer’s disease." (PMID 23986861, 2013). "Among our patients with Alzheimer's disease we did not detect APOE effects on cortical thickness; however, others have found regionally selective APOE-4 effects on the hippocampal region." (PMID 24228185, 2013). "The multivariate general linear model revealed significant main effects for cardiovascular risk (F = 4.41, df = 7,14, P = 0.009) and MMSE score (F = 9.15, df = 7,14, P < 0.001) but not for APOE genotype, family history of Alzheimer's disease, and age." (PMID 24228185, 2013). "CRP gene variation affects early SP development in prodromal Alzheimer's disease, independent of APOE genotype." (PMID 21831326, 2011). "The signature supports the role of APOE in lipid regulation through apolipoproteins and inflammation and includes, among others, neutrophil secreted granule proteins CAMP, CTSG, DEFA3, and MPO that point to inhibition of OLFM4 as a target for Alzheimer's disease therapeutics." (PMID 41316897, 2026). "Using ApoE proteotype as a standard to enroll participants for Alzheimer’s disease drug trials may not work." (PMID 40114255, 2025). "To address this, we generated cortical organoids 15,16 from induced pluripotent stem cell (iPSC) lines of two donors from the University of Kansas Alzheimer’s Disease Research Center cohort: a heterozygous APOE ε4 carrier who developed AD and a non-carrier control." (PMID 40709278, 2025). "However, longitudinal studies in early Alzheimer's disease (AD) are lacking and the relationship to the Apolipoprotein-E (APOE) genotype is unclear." (PMID 39788739, 2025). "In the current study, we found significantly smaller right hippocampus volumes in carriers of two APOE ε4 alleles relative to non-carriers, which is in line with previous work linking the APOE ε4 genotype to greater rates of hippocampal atrophy in non-demented and Alzheimer’s disease samples." (PMID 40439116, 2025). "Indeed, 1 previous mediation study showed that the mediated effects of APOE on cognition by non–Alzheimer disease neuropathologies were consistent, independent of presence of β-amyloid." (PMID 40344552, 2025). "In Alzheimer's disease, it is clear that APOE is not a progression locus when the analysis is restricted to those who have been diagnosed clinically but with evidence for amyloid pathology either by PET scan or biomarker analysis (consistent with the data summarised above)." (PMID 40600356, 2025). "It has been reported that the splicing of the APP, APOE, SNCA, MAPT, DAO, SHANK3, and CACNA1C genes, which are recorded in the PsyGeNET database, were abnormal in patients with neurological diseases such as Parkinson’s disease, Alzheimer’s disease, and amyotrophic lateral sclerosis." (PMID 39858933, 2025).
Alzheimer disease (continued). "The research has found a lower antioxidant capacity of plasma in patients with Alzheimer’s disease and controls expressing the APOE genotype 4/4 without cognitive damage, but have not found a lower antioxidant capacity when the subjects performed cognitive tasks better." (PMID 38675419, 2024). "Our results indicate that the Alzheimer’s disease PRS does not drive dementia in Lewy body diseases, suggesting that APOE e4 may drive dementia in these cases by an Alzheimer’s disease pathology-independent mechanism." (PMID 38978726, 2024). "Apolipoprotein E and IL-23/IL-17 may link psoriasis and Alzheimer’s dementia, the most common non-vascular dementia." (PMID 38378928, 2024). "A nasal delivery of a synthetic LXR agonist N,N-dimethyl-3β-hydroxycholenamide (DMHCA) alleviated cognitive impairment and increased brain ApoE content without changing the serum level of cholesterol and triglycerides in the Alzheimer’s disease model of McGill-Thy1-APP transgenic mice." (PMID 38627787, 2024). "Within tau-first APOE ε4 carriers, we found an increased rate of amyloid-β accumulation (via longitudinal amyloid PET), suggesting that this rare group may belong within the Alzheimer's disease continuum." (PMID 37433038, 2023). "Analysis of individual-specific functional connectivity can differentiate between normal ageing and Alzheimer Disease and individual-specific between-network connectivity constitute a major contributor for assessing cognitive symptoms in both APOE ε4 carriers and non-carriers." (PMID 37258640, 2023). "Both the activation of glycogen synthase kinase‐3β (GSK‐3β) and the presence of ApoE ε4 genotype have been found to respectively correlate with cognitive decline in patients with type 2 diabetes mellitus (T2DM), who further show a high incidence of developing Alzheimer's disease." (PMID 37700547, 2023). "The absence of APOE‐ε4 does not ensure protection from Alzheimer's disease." (PMID 36946865, 2023). "However, APOE ε4 dosage and baseline cognitive function did not significantly modify the relationships of glucosamine use with incident vascular dementia or Alzheimer’s disease (All P-interactions > 0.05)." (PMID 37689747, 2023). "People with APOE ɛ4 may also experience cognitive decline at a younger age compared to non-carriers, although not all APOE ɛ4 carriers will develop Alzheimer’s disease or experience significant cognitive decline." (PMID 37485386, 2023). "Genotypes from the National Institute on Aging Late‐Onset Alzheimer's Disease Family‐Based Study and a study of familial Alzheimer's disease in Caribbean Hispanics were used to compute PRS with and without variants in the 2 MB region flanking APOE." (PMID 36946865, 2023). "In Reduced Model 1, AP for the full PRS accounted for 10.1% (σ2Aᴩ = 0.101, CI95 = 0.051, 0.164) of variation contributing to Alzheimer’s disease risk, whereas, in Reduced Model 2, AP for the PRS.no.APOE accounted for 2.4% (σ2Aᴩ-APOE = 0.024, CI95 = 0.004, 0.065)." (PMID 35169705, 2022). "Recent data have shown that a 30-day medium-chain triglycerides intervention induced ketosis, increased concentrations of LPC 16:0, P-18:1, P-18:0, 20:2, and 22:5, and improved cognitive function in patients with mild to moderate Alzheimer’s disease who are not apolipoprotein E ɛ4 carriers." (PMID 35389191, 2022). "In this present study, we mainly investigated the effects of CSF GAP-43 on cognitive impairment and whether the roles of GAP-43 were related to APOE ε4 status among cognitively normal (CN) controls, MCI and AD participants from the Alzheimer’s Disease Neuroimaging Initiative (ADNI) database." (PMID 36611808, 2022). "Besides, various gene mutations closely associated with mitochondrial function, including those involving amyloid precursor protein (APP), presenilin 1 (PSEN1), 46 presenilin 2 (PSEN2), apolipoprotein E (ApoE) and a disintegrin and 71 metalloprotease 10 (ADAM10), lead to Alzheimer’s disease." (PMID 33686350, 2021).
Alzheimer disease (continued). "A further study of 162 adults who had a living or deceased parent with Alzheimer’s disease and were randomized to receive or not receive their own APOE genotype showed that some participants randomized to the nondisclosure group were dissatisfied at not receiving their genotyping results." (PMID 34748551, 2021). "However, some caution is warranted since these observations on defective pruning were made in the development of Alzheimer’s disease and it is not clear if APOE would have a similar involvement in synaptic pruning at earlier stages." (PMID 33670154, 2021). "Similarly, cognitively healthy preclinical adults (defined by APOE genotype or Alzheimer’s disease pathologies), as well as MCI and Alzheimer’s disease patients, also perform significantly worse in tests of feature binding, showing a marked decline in representational fidelity." (PMID 33987536, 2021). "In apolipoprotein E (APOE) ε4-carriers, linear relationships were found between greater cognitive decline/year and higher tau; Mini-Mental State Examination score – T-tau (rs = − 0.257, p = 0.014) and Alzheimer’s Disease Assessment Scale–cognitive subscale – P-tau (rs = − 0.242, p = 0.022)." (PMID 31918679, 2020). "Luck and colleagues analyzed data from the German study on Ageing, Cognition and Dementia in Primary care Patients (AgeCoDe) and reported no GxE interaction in multiplicative scale between APOE ɛ 4 and PA in dementia but they found a possible additive interaction in Alzheimer’s disease." (PMID 32110803, 2020). "However, not all APOE ε4 carriers will develop Alzheimer disease, thereby suggesting the interactive effects of APOE genotype with other genetic or environmental factors." (PMID 32379048, 2020). "Subjects with MCI in the Alzheimer's Disease Neuroimaging Initiative (ADNI) database, with baseline data for neuropsychological tests, brain beta amyloid (Abeta), magnetic resonance imaging (MRI), APOE genotyping, and 18F-FDG-PET (FDG), were included for analysis." (PMID 33178360, 2020). "We demonstrate this using Alzheimer's Disease Neuroimaging Initiative (ADNI) data, where we model longitudinal trajectories of MRI‐derived cortical volumes in neurodegeneration, with coupling based on APOE genotype, cerebrospinal fluid (CSF) and amyloid PET‐based biomarkers." (PMID 31168892, 2019). "Likewise, distinct patterns of striatal atrophy and increased Aβ deposition, but not metabolic change, have been observed in ApoE ε4 carriers compared to non-carriers in Alzheimer's disease." (PMID 30991617, 2019). "APOE3- and APOE4-TR mice are mostly used in exploring the roles for direct comparison studies to measure the effects human apoE3 and apoE4 in normal brain physiology and Alzheimer’s disease, while the effects of murine apoE of wild type mice were not generally covered." (PMID 30700991, 2019). "By using a well-characterized cohort of AD patients and control individuals, authors found a genetic association for the CaSR with AD status only in subjects without an apolipoprotein E (APOE) e4 allele, which is reported to be a susceptibility gene for late-onset Alzheimer’s disease." (PMID 31336912, 2019). "Although authors did not observe a difference between the APOE genotypes of CTE subjects with dementia from those seen in patients with Alzheimer’s disease, notably they found a greater proportion of ε4 homozygotes in CTE patients than expected in a normal, age-matched population." (PMID 30223506, 2018). "Therefore, the effects of APOE protein isoforms on cholesterol and lipid metabolism are faithfully represented in animal models but these models do not display typical Alzheimer’s disease hallmarks as a consequence of human APOE4 isoform protein expression." (PMID 28094792, 2017).